CCND1 (cyclin D1)
Diseases named in the same sentence as CCND1 in open-access papers (continued):
Sharing a sentence is not in itself a finding about the gene and the disease.
gastric cancer (285 papers, 2005 to 2026). A primary or metastatic malignant neoplasm involving the stomach. "CCND1 is associated with cancer development and is frequently overexpressed in various human cancer cells and tissues, including gastric cancer." (PMID 40145254, 2025). "Additional IHC analysis confirmed a significant association between GABRD and CCND1 protein expressions in gastric cancer tissues (p = 0.00917)." (PMID 40145254, 2025). "Several reports have shown that CCND1 overexpression is associated with shorter survival in patients with gastric cancer." (PMID 40145254, 2025). "Signalling pathways involving cyclin D1 have previously been implicated in the development of EMT in gastric cancer and other cancers." (PMID 41148809, 2025). "Kruppel-like factor 5 (KLF5) is correlated with a worse prognosis of gastric cancer and is positively associated with Cyclin D1 in gastric cancer, as observed in MGC803 and SGC7901 cell lines." (PMID 36769170, 2023). "The increased expression of cyclin D1 has been associated with decreased G1 phase distribution and with decreased survival in many common cancers including gastric cancer." (PMID 24618206, 2014). "Cyclin D1 upregulation has been implicated as a driver of gastric cancer, and its inhibition has been shown to reverse the transformed phenotype of human gastric cancer cells." (PMID 16552434, 2006). "Increased cyclin D1 expression has been shown to be associated with uncontrolled gastric cancer cell proliferation." (PMID 16552434, 2006). "Tetrahydroxycurcumin (200 mg/kg‐1 orally administered for 3 and 20 weeks) was found to reduce the phosphorylated inhibitor kappaB alpha, cyclin D1, and 8‐hydroxy‐2‐deoxy‐guanosine in a rat model of gastric cancer caused by N‐methyl‐N‐nitrosourea and saturated sodium chloride." (PMID 41179371, 2025). "Contrary to our findings, a study revealed that reduced overall and progression-free survival is linked to overexpression of CCND1 in gastric cancer and also linked to poor differentiation and negative erb2 status, emphasizing its prognostic significance in gastric cancer." (PMID 39188436, 2024). "GLIS2 could also regulate the interaction between β-catenin and T-cell factor/Lymphoid enhancer factor (TCF/LEF) to affect the activation of cyclin D1, which may have association with poor tumor differentiation and prognosis in gastric cancer." (PMID 31281358, 2019). "Therefore the CORO1C–cyclin D1–vimentin pathway is in turn associated with the prognosis of gastric cancer patients." (PMID 30974047, 2019). "We also found that mRNA expression levels of CDH1, CDKN1A, and EP300 were significantly reduced while those of RhoA, ROCK1, ROCK2, PIK3CA, and CCND1 were significantly increased in gastric cancers with reduced or loss of NKX6.3 expression compared to those in NKX6.3 positive cases." (PMID 30514953, 2018). "In addition, expression levels of CDH1, CDKN1A, and EP300 were reduced while expression levels of RhoA, ROCK1, ROCK2, PIK3CA, and CCND1 were increased in gastric cancer tissues with reduced or loss of NKX6.3 expression." (PMID 30514953, 2018). "In addition, some polymorphic genes encoding metabolic enzymes and cell cycle regulators, such as methylene tetrahydrofolate reductase, NADPH: quinone oxidoreductase and Cyclin D1 have been documented to confer a susceptibility to gastric cancer." (PMID 24505369, 2014). "Importantly, the tumorigenicity of gastric cancers was significantly suppressed by restoring miR-9 expression in miR-9-deficient gastric cancers, thereby reducing the expression of the cyclin D1 and Ets1 oncogenes." (PMID 25717380, 2014). "In addition, the association between ER-α36 and cyclin D1 in the SGC7901 gastric cancer cells was induced by E2β." (PMID 24137325, 2013). "In addition, the expression of the cyclin D1 and p27Kip1 proteins is inversely correlated and is associated with a poor clinical outcome in human gastric cancer." (PMID 18268498, 2008).
gastric cancer (continued). "Cyclin D1 expression at high levels has been associated significantly with poor prognosis of gastric cancer, as observed in gastric cancer samples in which CD44 expression was also higher, indicating a coexpression of these proteins could be a potential biomarker for the severity of the disease." (PMID 36769170, 2023). "CCND1 has been associated with gastric cancer, and its polymorphisms have been hypothesized to mediate risk for periodontitis-linked oral cancer, suggesting similar phenomena in gastric cancer." (PMID 35132337, 2022). "Cyclin D1 and vimentin might mediate the oncogenicity in human gastric cancer caused by CORO1C." (PMID 30974047, 2019). "For instance, RNF181 can modulate signaling pathways that involve Hippo/YAP, CARD11 and ERK/MAPK-cyclin D1/CDK4, and it has been implicated in diseases like triple negative breast cancer and gastric cancer." (PMID 41494040, 2026). "In contrast, SIRT1 activation inhibits cyclin D1 transcription and cell growth in gastric cancer, suggesting two aspects of SIRT1 activation in promoting or suppressing tumor growth." (PMID 39940750, 2025). "TCGA‐STAD data revealed CCND1 mRNA levels significantly elevated in gastric cancer compared to normal tissues, corroborated by analysis of 27 paired samples." (PMID 40145254, 2025). "In our present study, we found that high CCND1 expression levels are correlated with shorter overall survival of gastric cancer patients." (PMID 40145254, 2025). "METTL16 enhances the stability of CCND1 mRNA through methylation modification, thereby increasing CCND1 expression and promoting the proliferation of gastric cancer cells." (PMID 41194259, 2025). "First, we analysed CCND1 expression levels in gastric cancer cell lines and a normal gastric mucosal epithelial cell line (GES1) by qRT‐PCR." (PMID 40145254, 2025). "A potential relationship between GABAergic signaling and CCND1 in gastric cancer has also been reported in the literature." (PMID 40145254, 2025). "Our findings identify GABRD as a novel oncogene in gastric cancer, promoting malignant phenotypes through CCND1‐dependent cell cycle regulation." (PMID 40145254, 2025). "NHE1 promotes cell proliferation in gastric cancer by modulating the G1/S and G2/M cell cycle transitions, while upregulating positive cell cycle regulators like cyclin D1 and cyclin B1 in gastric cancer cells." (PMID 38370477, 2024). "For instance, curcumin, a polyphenol derived from turmeric (Curcuma longa), inhibits the expression of cyclin D1, reduces Ki67 expression through modulation of the NF-κB signaling pathway, and suppresses the proliferation of gastric cancer cells." (PMID 39906672, 2024). "METTL16 upregulates cyclin D1 expression by enhancing cyclin D1 mRNA stability through m6A modification, which in turn accelerates the G1/S phase transition to promote gastric cancer cell proliferation." (PMID 39289775, 2024). "NCAPD3 loss can directly inhibit CCND1 and ESR1 expression to downregulate the expression of downstream targets CDK6 and IRS1 and inhibit the proliferation of gastric cancer cells." (PMID 38711992, 2024). "Upregulation of hsaMrs2p expression in gastric cancer cells leads to increased intracellular Mg2+ and upregulation of cyclin D1, resulting in multidrug resistance." (PMID 38370477, 2024). "For example, AURKB accelerates the tumor growth of gastric cancer via activating the expression of cell cycle regulator CCND1 through pH3S10." (PMID 38713155, 2024). "In gastric cancer cells, c-Myc up-regulates Cyclin D1 expression, while in rabbit embryo cells, c-Myc down-regulates Cyclin D1 expression." (PMID 36674593, 2023). "Epstein–Barr virus has been associated with gastric carcinomas and EBV oncogene BARF1 stabilizes and interacts with Cyclin D1 at transcriptional and protein levels in gastric cancer." (PMID 36769170, 2023).
gastric cancer (continued). "IC53d promotes gastric cancer cell proliferation and invasive phenotypes via the promotion of GSK3b and Akt phosphorylations, further increasing Cyclin D1 and G1 to S phase transition." (PMID 36769170, 2023). "Alterations in CDKN2A-CDK4/6/CCND1 machinery were frequently observed in gastric cancer patients (TCGA)." (PMID 36755269, 2023). "Methyltransferase-like 3 (METTL3) modifying mRNA via N6-methyladenosine is involved in gastric cancer, whereby it upregulates Cyclin D1 levels and activates the Akt signaling pathway, as shown in loss-of-function experiments in gastric cancer cells." (PMID 36769170, 2023). "Various factors downregulate the activity of Cyclin D1 in gastric cancer cells and are discussed here in detail." (PMID 36769170, 2023). "An Interleukin 6 cytokine family member known as Leukemia inhibitory factor (LIF) downregulates Cyclin D1 and upregulates p21 in gastric cancer cells under both in vivo and in vitro conditions." (PMID 36769170, 2023). "It facilitates the phosphorylation of H3 at S10, which in turn leads to the transcription of CCND1 and upregulation of Cyclin D1 under in vitro and in vivo conditions in gastric cancer." (PMID 36769170, 2023). "RUNX3 induces cell cycle arrest and inhibits cell proliferation of gastric cancer cells by inactivating Akt1/β-catenin/cyclin D1 signaling pathway." (PMID 38093179, 2023). "Its overexpression in gastric cancer cell lines led to a reduction of survivin, Cyclin D1, c-myc, and β-catenin." (PMID 36769170, 2023). "A long non-coding RNA (HOTAIR) targets miR-454-3p to upregulate the STAT3/Cyclin D1 in gastric cancer cells to promote the proliferation and progression of cancer." (PMID 36769170, 2023). "In MGC-803 cells, Resveratrol treatment leads to the inhibition of Cyclin D1, along with c-myc and β-catenin, indicating that Cyclin D1 regulation is influenced by c-myc and β-catenin in gastric cancer cells." (PMID 36769170, 2023). "LINC0857 is a long non-coding RNA that upregulates Cyclin D1 and Cyclin E1 for the progression of gastric cancer and has been indicated as a potential biomarker for the prognosis and diagnosis of the disease." (PMID 36769170, 2023). "The Enhancer of Zeste Homolog 2 (EZH2), functioning as a polycomb protein, also upregulates Cyclin E in gastric cancer cells, as its inhibition leads to Cyclin D1 and Cyclin E downregulation." (PMID 36769170, 2023). "Cyclin D1 protects gastric cancer cells from Doxorubicin, where p73 modulates Cyclin D1 levels positively with the help of activator protein 1 (AP-1)." (PMID 36769170, 2023). "A recent study has shown that METTL16 promotes gastric cancer proliferation by up-regulating cyclin D1 expression." (PMID 37340443, 2023). "SIX1 regulation of Cyclin D1 implies that Cyclin D1 is at the crossroads of multiple cellular signaling pathways involved in the progression of gastric cancer." (PMID 36769170, 2023). "Another oncogene giving rise to WDR5 protein is increased in gastric cancer, where it induces H3K4me3 and Cyclin D1 for the progression of the cell cycle and tumorigenesis." (PMID 36769170, 2023). "For example, ESRRG has been shown to antagonize the proliferation of gastric cancer cells by suppressing TCF4/LEF1 binding to the CCND1 promoter, highlighting its tumor suppressor role." (PMID 37679788, 2023). "An m6A methyltransferase (METTL16) that modifies RNA via N6-methyladenosine (m6A) functions to upregulate Cyclin D1 transcription through its methyltransferase activity in gastric cancer cell proliferation." (PMID 36769170, 2023). "For example, lncRNA SUNO1 promotes cell cycle progression by controlling the YAP1/Hippo signaling pathway; miR-218 suppresses gastric cancer cell cycle progression via the CDK6/Cyclin D1/E2F1 axis." (PMID 37538116, 2023).
gastric cancer (continued). "Dihydroartemisinin (DHA) exerts its anti-tumor activities through inhibition of CDK4 activity and targets Cyclin D1 negatively for induction of cell cycle arrest under in vivo and in vitro conditions in gastric cancer." (PMID 36769170, 2023). "There are various upstream regulators of Cyclin D1 that act as oncogenes for the progression of normal gastric cells to gastric carcinoma." (PMID 36769170, 2023). "As a result, KLF13 inhibited gastric cancer proliferation by triggering the autophagic degradation of β-catenin and reduced expressions of Cyclin D1 and c-Myc." (PMID 36336731, 2022). "The ability of NLRP3 to bind to the CCND1 promoter and to support its transcription was already described in gastric cancer." (PMID 35745570, 2022). "Western blot analysis was performed to detect the expression of claudin 1, c-Myc, cyclin D1, Bcl-2, and caspase-3 proteins in gastric cancer cell lines after treatment with miR-155-5p and Res." (PMID 35789645, 2022). "Taken together, these data suggest the involvement of PAR-1, PI3K/Akt signaling and cyclin D1 in ncRuPAR-mediated gastric cancer cell proliferation and apoptosis." (PMID 36438913, 2022). "In vivo, KLF13 overexpression also suppressed xenograft tumor growth of gastric cancer and down-regulated expressions of Ki67, β-catenin, Cyclin D1, and c-Myc in tumor tissues." (PMID 36336731, 2022). "NLRP3 inflammosomes enhance the differentiation of gastric cancer cells by participating in cyclin-D1 and inducing IL-1β production." (PMID 35153782, 2022). "HOXC10 is a target of miR-129-5p, and miR-129-5p inhibits gastric cancer development by regulating HOXC10/Cyclin D1 axis." (PMID 35201457, 2021). "CCND1 (Cyclin D1) overexpression correlated with poor tumor differentiation and prognosis in gastric cancer." (PMID 34895232, 2021). "Subsequently, Silencing EME1 in two gastric cancer cell lines decreased the expression of Akt, CCND1, and GSK3B as well as the phosphorylation levels of Akt, CCND1, and GSK3B." (PMID 34719326, 2021). "The researchers demonstrated that miR‐194 controls CCND1 levels in two different sets of gastric cancer cells, strengthening their findings." (PMID 34081843, 2021). "In particular, they show increased miR‐194 levels are a predictor of more favourable gastric cancer prognosis, at least in part due to miR‐194 downregulating production of a key protein for cancer development: CCND1." (PMID 34081843, 2021). "CCND1 gene is abnormally expressed in various tumors, such as glioma, cervical cancer, and gastric cancer." (PMID 34806539, 2021). "YWHAG promoted gastric cancer proliferation and metastasis and inhibited cell apoptosis by activating Ras signaling to enhance Cyclin D1 and inhibit p21 and p27, which are key proteins in G1 of the cell cycle." (PMID 34168120, 2021). "Simvastatin sensitizes gastric cancer to capecitabine in human gastric cancer xenografts by inhibiting NF-κB activation and abrogation of cyclin D1, cyclooxygenase-2 (COX-2), survivin, Bcl-2, CXC motif receptor 4, and MMP-9." (PMID 34065757, 2021). "Previously, increased transcription levels of c-myc, cyclin D1, c-jun, Wisp1 and Birc5 in the development and progression of gastric cancer were reported." (PMID 34594214, 2021). "In gastric cancer cells, CSMD1 downregulation has been associated with increased NF‐κB signalling, upregulation of c‐Myc and CCND1, and downregulation of E‐cadherin." (PMID 33506581, 2021). "Our findings were consistent with these data, suggesting that metastatic gastric cancer cells exhibited more malignant behaviors via upregulating the expression of Cyclin D1 and PCNA." (PMID 32139657, 2020). "We demonstrate that cyclin D1 (CCND1) is a direct downstream target of AURKB that plays a key role in gastric cancer cell proliferation." (PMID 31982864, 2020).
gastric cancer (continued). "Taken together, these data suggested that metastatic gastric cancer cells exhibited significant proliferative ability via increasing the expression of Cyclin D1 and PCNA." (PMID 32139657, 2020). "We showed that the enrichment of H3S10ph in the gene promoter of CCND1 was indeed markedly lower when AURKB was knocked down in gastric cancer cells than in scrambled control cells." (PMID 31982864, 2020). "Curcumin inhibits Bcl-2, Bcl-XL, VEGF, c-Myc, ICAM-1, EGFR, STAT3 phosphorylation, and cyclin D1 genes involved in the various stages of breast, prostate, and gastric cancer proliferation, angiogenesis, invasion, and metastasis." (PMID 33178666, 2020). "Ant-proliferative activity of the dual AKT/mTOR inhibitor, BEZ235, correlated with a dose-dependent increase of gastric cancer cells in the G1 phase of the cell cycle and cyclin D1 downregulation." (PMID 33659215, 2020). "We showed that the inhibition of AURKB kinase activity by AZD1152 repressed CCND1 expression in gastric cancer cells and decreased cell proliferation in vitro." (PMID 31982864, 2020). "Significant gains of genes ATAD2, DSCC1, FAM91A1, and MYC brought to the enrichment of the Gastric Cancer Network 2 pathway, and ATAD2 is a cancer-associated protein which can also induce the expression of Cyclin D1 and MYC." (PMID 31921654, 2019). "And the constitutive activation of STAT3 and CCND1 overexpression is accounted for the proliferation, migration and invasion in gastric cancer cells." (PMID 30143675, 2018). "c-MYC and CCND1 are downstream target genes of Wnt signaling, which suggests that EphA2 overexpression indeed enhances Wnt signaling in gastric cancer." (PMID 30451837, 2018). "Mechanism researches suggested that SIRT1 can counteract the activation of STAT3 and NF-κB to repress cell growth and lead to G1-phase arrest via NF-κB/Cyclin D1 signaling in gastric cancer." (PMID 29088792, 2017). "In gastric cancer, gastrin is responsible for not only inducing acid secretion but also stimulating a number of oncogenic pathways, such as cyclin D1 and β‐catenin pathways 22, to induce cancer progression." (PMID 28781948, 2017). "Our results indicated that c-Myc up-regulated Cyclin D1 expression by binding to the Cyclin D1 promoter in gastric cancer cells." (PMID 28915664, 2017). "ZHX1 has been reported to induce apoptosis and cell cycle arrest (G1/S) by regulating cyclin D1, cyclin E, Bcl2, Bax, and cleaved caspase-3 in gastric cancer, and ZHX2 overexpression was correlated with low expressions of cyclin A and cyclin E in HCC." (PMID 28152006, 2017). "A number of NF-κB-regulated gene products, including cyclin D1, COX-2, etc. have been closely linked with the development of chemoresistance in gastric cancer." (PMID 28350359, 2017). "It was also identified as being down-regulated in gastric cancer and a key regulator of NFκB/Cyclin D1 signaling and G1 phase arrest, offering a possible therapeutic intervention in biological models." (PMID 27384994, 2016). "Published data on the association between cyclin D1 (CCND1) G870A polymorphism and gastric cancer (GC) risk are inconclusive." (PMID 27623072, 2016). "MiR-15b and miR-16 in combination with chemotherapy can induce the sensitivity of gastric cancer cells by inhibition of cyclin D1 (BCL1)." (PMID 27790245, 2016). "In this study, we observed that YM155 markedly suppressed formation and expansion of spheres in gastric cancer cells and downregulated expression of β-catenin, c-Myc and Cyclin D1, which are downstream genes of Wnt/β-catenin signaling." (PMID 26771139, 2016).